ZC3H12C (zinc finger CCCH-type containing 12C)
Description:
May function as RNase and regulate the levels of target RNA species.
Synonyms: KIAA1726; MCPIP3
Tractability: No criterion of Open Targets' tractability assessment is met for any kind of drug.
Gene: Protein-coding gene on chromosome 11 (110,093,392 to 110,171,841, forward strand). Ensembl gene ENSG00000149289.
Subcellular location (Human Protein Atlas): Golgi apparatus; Nuclear membrane
Gene Ontology:
Molecular function: protein binding; mRNA binding; RNA endonuclease activity; metal ion binding
Biological process: 3'-UTR-mediated mRNA destabilization
Cellular component: cytoplasmic ribonucleoprotein granule; nucleus
Genetic constraint (gnomAD): Loss-of-function variants: 20 observed, 74.76 expected, observed/expected ratio (o/e) 0.27, 90% interval 0.19 to 0.39. The upper end of that interval is the gene's LOEUF score, 0.39, which puts it in group 1 of 6, group 1 being the genes least tolerant of losing a copy. Missense variants: 874 observed, 1,129 expected, observed/expected ratio (o/e) 0.77, 90% interval 0.73 to 0.82. Synonymous variants: 352 observed, 419.17 expected, observed/expected ratio (o/e) 0.84, 90% interval 0.77 to 0.92.
Homologues: Orthologues: chimpanzee ZC3H12C (99% identical), macaque ZC3H12C (97% identical), rabbit ZC3H12C (93% identical), pig ZC3H12C (93% identical), mouse Zc3h12c (92% identical), rat Zc3h12c (92% identical), dog ZC3H12C (89% identical), guinea pig ZC3H12C (89% identical), tropical clawed frog zc3h12c (71% identical), Caenorhabditis elegans rege-1 (23% identical), Drosophila melanogaster Regnase-1 (22% identical), Drosophila melanogaster CG42360 (12% identical), and 3 more. Paralogues in human: ZC3H12B (50% identical), ZC3H12A (32% identical), ZC3H12D (25% identical), NYNRIN (19% identical), N4BP1 (15% identical), KHNYN (14% identical).
Diseases named in the same sentence as ZC3H12C in open-access papers:
ZC3H12C is named in the same sentence as 37 diseases in open-access papers, as found by Europe PMC text mining. Sharing a sentence is not in itself a finding about the gene and the disease. The quoted sentences say what the papers report.
psoriasis (5 papers, 2021 to 2025). An autoimmune condition characterized by red, well-delineated plaques with silvery scales that are usually on the extensor surfaces and scalp. "In humans, single nucleotide polymorphisms (SNPs) in ZC3H12C have been recognized as a risk factor for psoriasis susceptibility in several genome-wide association studies." (PMID 40283629, 2025). "Studies have shown that ZC3H12C negatively regulates the immune control of psoriasis by inhibiting NF-κB signaling and proinflammatory gene expression in endothelial cells." (PMID 35795311, 2022). "In order to determine if this increased MCPIP3 expression is correlated with psoriasis, we analyzed human ZC3H12C transcripts from psoriasis patient biopsies (GEO: GDS3539; GDS4600) 30,31." (PMID 34215755, 2021). "We found that ZC3H12C transcripts were significantly higher in lesional skin than non-lesional skin from the same psoriasis patients." (PMID 34215755, 2021). "Lastly, to exclude the possibility that any expression of Zc3h12c in nonhematopoietic cells, such as keratinocytes, langerin cells, and tissue-resident macrophages, may play a role in psoriasis, we generated reverse chimeras from Zc3h12c−/− mice." (PMID 34215755, 2021).
colorectal cancer (4 papers, 2018 to 2025). A primary or metastatic malignant neoplasm that affects the colon or rectum. "The involvement of ZC3H12C in colorectal cancer has been previously reported, whereas the role of SLC19A1 remains unexplored." (PMID 41376620, 2025). "Some studies have also shown that ZC3H12C is negatively correlated with lung adenocarcinoma and colorectal cancer." (PMID 35795311, 2022). "Reduced expression of ZC3H12C may disrupt the regulation of inflammatory responses and immune tolerance in the tumor microenvironment, thereby facilitating colorectal cancer progression through enhanced immune evasion and tumor cell survival." (PMID 41376620, 2025). "Results showed that ZC3H12C was weakly marked in colorectal cancer and mainly located in cytoplasm." (PMID 38267865, 2024).
colon adenocarcinoma (2 papers, 2022 to 2024). "The results demonstrated that ZC3H12C expression was significantly lower in colon adenocarcinoma (COAD) and rectal adenocarcinoma (READ) than normal tissues." (PMID 38267865, 2024). "In addition, the positive correlations between ZC3H12C expression and highly connected CD8+ T genes were also visualized, including CD8A, CD8B, GZMA, GZMB, and PRF1 in colon adenocarcinoma and rectum adenocarcinoma." (PMID 38267865, 2024).
chronic kidney disease (1 paper, 2025). Impairment of the renal function secondary to chronic kidney damage persisting for three or more months. "Both Tnfrsf11a and Zc3h12c are highly expressed in the kidney tissue from patients with chronic kidney disease and showed a positive association with an interstitial fibrosis score." (PMID 40834429, 2025).
esophageal carcinoma (1 paper, 2022). A primary or metastatic malignant neoplasm involving the esophagus. "First, the high ZC3H12C expression is associated with favorable outcomes in ESCA (esophageal carcinoma), KIRC, and PAAD (pancreatic adenocarcinoma), while the opposite is true in LUAD, STAD (stomach adenocarcinoma), THYM (thymoma), and UCEC." (PMID 35795311, 2022). "The same was true for STAD and STES (stomach and esophageal carcinoma) but not for THYM in which the high ZC3H12C expression is significantly associated with poor prognosis." (PMID 35795311, 2022).
experimental autoimmune encephalomyelitis (1 paper, 2021). An autoimmune demyelinating disease of the central nervous system that is produced experimentally in animals by the injection of homogenized brain or spinal cord in Freund's adjuvant. "Using a Th17-driven experimental autoimmune encephalomyelitis (EAE) model, we found that the EAE clinical score and Th17 responses in Zc3h12c+/+ and Zc3h12c−/− mice were similar." (PMID 34215755, 2021).
Lymphadenopathy (1 paper, 2021). Enlargement (swelling) of a lymph node. "MCPIP3 (also named Regnase-3; encoded by Zc3h12c)-deficient mice were also healthy, despite some lymphadenopathy and an increase in serum interferon (IFN)-γ24." (PMID 34215755, 2021).
melanoma (1 paper, 2021). A malignant, usually aggressive tumor composed of atypical, neoplastic melanocytes. "On the other hand CYT-low metastatic melanomas had recurrent amplifications in loci 5p15.33 (TERT), 6p25.1 (CDYL), 7p22.2 (RAC1), 12q15 (MDM1) and recurrent deletions in 5q31.2 (CTNNA1, FGF1), 11q22.3 (FDX1, RDX, ZC3H12C), and 15q14 (RASGRP1, CSNK1A1P1, SPRED1)." (PMID 33779796, 2021).
nephrocalcinosis (1 paper, 2025). Nephrocalcinosis is a disorder that occurs when too much calcium is deposited in the kidneys. "To further study the role of Mφ Zc3h12c in other type of tissue injury, we fed mice an oxalate‐rich diet to induce nephrocalcinosis‐related progressive kidney injury." (PMID 40834429, 2025).
ovarian serous cystadenocarcinoma (1 paper, 2022). A malignant serous cystic epithelial neoplasm arising from the ovary. "In addition, using normal tissues from the GTEx data as controls, we further confirmed with GEPIA that ZC3H12C was significantly lower in OV (ovarian serous cystadenocarcinoma) and UCS (uterine carcinosarcoma)." (PMID 35795311, 2022).
renal clear cell carcinoma (1 paper, 2022). "Through comparative analysis of the Cancer Genome Atlas (TCGA) database, we found that ZC3H12C is the most relevant to the prognosis, grade, and stage of renal clear cell carcinoma (ccRCC) across 33 cancers." (PMID 35795311, 2022).
sarcoma (1 paper, 2022). A usually aggressive malignant neoplasm of the soft tissue or bone. "In addition, the ZC3H12C expression was significantly lower in ACC (adrenocortical carcinoma), PRAD, SARC (sarcoma), and SKCM (skin cutaneous melanoma)." (PMID 35795311, 2022).
cancer (9 papers, 2018 to 2025). A tumor composed of atypical neoplastic, often pleomorphic cells that invade other tissues. "We found that the ZC3H12C gene is underexpressed across several cancer types and associated with survival." (PMID 35795311, 2022). "Therefore, we further investigated the associations between immune cell infiltrations and ZC3H12C in multiple cancer types using TISIDB." (PMID 38267865, 2024). "In conclusion, in our first pan-cancer analysis, we show that ZC3H12C is comprehensively downregulated in tumor tissues, and we reveal its potential functions in clinical prognosis." (PMID 35795311, 2022). "In this study, for the first time through pan-cancer analysis, we found that ZC3H12C was significantly downregulated in human cancers, especially in 13 cancers." (PMID 35795311, 2022). "This study showed the downregulation and clinical significance of ZC3H12C in different human cancers and, for the first time, we proved its antitumor effect in KIRC." (PMID 35795311, 2022). "Compared to other cancers, in KIRC, high level of ZC3H12C is most significantly associated with longer OS." (PMID 35795311, 2022). "The differential expression of ZC3H12C in different cancers is likely due to its corresponding biological functions." (PMID 35795311, 2022). "Based on the TCGA data set, we analyzed the ZC3H12C expression in different types of cancer and found a correlation between its expression and the prognoses for different patients." (PMID 35795311, 2022). "First, we analyzed the expression of ZC3H12C in different cancer types in the TCGA database by searching for TIMER2.0." (PMID 35795311, 2022). "The seven hub RBPs CD3EAP, POP5, NOP10, ATXN1, ZC3H12C, RBPMS, and SBDS were implicated in the progression and prognosis of many cancers." (PMID 36262474, 2022). "In addition, protein phosphorylation and DNA methylation analysis also showed that ZC3H12C negatively regulates the role of cancer in ccRCC." (PMID 35795311, 2022). "Nonetheless, further research is required to unravel the specific role of ZC3H12C in each cancer." (PMID 35795311, 2022). "The specific role of ZC3H12C in each cancer may have a lot to do with the heterogeneity of the cancer itself, and further in-depth experimental verification is needed." (PMID 35795311, 2022). "We found that ZC3H12C methylation can be used as a prognostic biomarker in cancer patients." (PMID 35795311, 2022). "Studies have shown that ZC3H12C may be involved in the occurrence and progression of human cancers." (PMID 35795311, 2022). "However, there are few reports on FASTKD3 and ZC3H12C involved in cancer." (PMID 36118863, 2022). "We speculate that ZC3H12C may have other complex mechanisms in these two cancers." (PMID 35795311, 2022). "Interestingly, the expression of ZC3H12C in CHOL and HNSC is significantly higher than that of adjacent cancers." (PMID 35795311, 2022). "Five—Using STRING database, we found that it had interactions with several proteins involved in different cancers such as TXNDC9, GXYLT2, POFUT1, XXYLT1, FLNA, and ZC3H12C." (PMID 35140741, 2021). "Some identified prognostic DE RBPs have not been associated with cancers, such as CELF4, POP1, TDRD6, TDRD7, LRRFIP2, and ZC3H12C." (PMID 33224957, 2020).
tumor (7 papers, 2018 to 2025). "KEGG pathway analysis indicated that ZC3H12C was involved in cell cycle and DNA replication pathways that are associated with tumor progression." (PMID 38267865, 2024). "Using the UALCAN database, we found that methylation of the ZC3H12C promoter increased in tumor tissues and was significantly linked to tumor grade." (PMID 35795311, 2022). "Univariate analysis showed that ZC3H12C expression, age, T stage, N stage, M stage, and tumor grade are all related to patient prognosis, while multivariate analysis revealed that ZC3H12C expression, age, and M stage are linked to patient survival." (PMID 35795311, 2022). "This indicates a potential role of ZC3H12C in modulating the tumor immune microenvironment by influencing CD8 + T cell infiltration." (PMID 38267865, 2024). "To assess the clinical features of ZC3H12C expression, we used the TNMplot and TIMER website to examine the expression of ZC3H12C in various tumor tissues and normal tissues." (PMID 38267865, 2024). "Both tumor volumes and tumor weights were significantly diminished after circRNF216 overexpression, while ZC3H12C knockdown enhanced the tumor volumes and tumor weights." (PMID 38267865, 2024). "We used the CPTAC dataset to compare the differences in ZC3H12C phosphorylation levels in paracancerous and primary tumor tissues in KIRC." (PMID 35795311, 2022). "Rescue experiments using miR-576-5p mimics and inhibitors were performed to explore whether circRNF216 exerted the tumor-suppressive effects via the circRNF216/miR-576-5p/ZC3H12C axis." (PMID 38267865, 2024). "To explore the immune cells infiltration in tumor tissues, we conducted flow cytometry analysis and found that circRNF216 overexpression enhanced the number of tumor-infiltrating CD8+ T cells, while ZC3H12C knockdown decreased tumor infiltrating CD8+ T cells in C57BL6 mice." (PMID 38267865, 2024). "Through its role in tumor immunity, ZC3H12C plays a prognostic role in ccRCC." (PMID 35795311, 2022). "In this work, we show that ZC3H12C may influence prognosis by negatively regulating immune infiltration of tumor cells in KIRC by affecting Tregs." (PMID 35795311, 2022). "CD3EAP, NOP10, and POP5 were significantly up-regulated in tumor tissue samples, while ATXN1, RBPMS, SBDS, and ZC3H12C were significantly downregulated in tumor tissue samples calculating by DESeq2 and edgeR, which were consistent with our previous results." (PMID 36262474, 2022). "Compared to normal samples, ATXN1, RBPMS, SBDS, and ZC3H12C were downregulated, and CD3EAP, NOP10, and POP5 were upregulated in UCEC tumor samples." (PMID 36262474, 2022).
ZC3H12C also shares sentences with these, for which no sentence is quoted: rectal adenocarcinoma (2 papers); autoimmune disease (1); bladder urothelial carcinoma (1); breast invasive carcinoma (1); chronic hepatitis B (1); depression (1); focal segmental glomerulosclerosis (1); glioma (1); glomerular diseases (1); IgA nephropathy (1); infection (1); lung adenocarcinoma (1); lung squamous cell carcinoma (1); membranous nephropathy (1); mesothelioma (1); pancreatic adenocarcinoma (1); prostate adenocarcinoma (1); skin cutaneous melanoma (1); stomach adenocarcinoma (1); thymoma (1); thyroid carcinoma (1); uterine carcinosarcoma (1); uterine corpus endometrial carcinoma (1).